BDNF (brain derived neurotrophic factor)
Diseases named in the same sentence as BDNF in open-access papers (continued):
Sharing a sentence is not in itself a finding about the gene and the disease.
Cognitive impairment (continued). "Notably, it is widely accepted that high levels of BDNF are associated with lower risk of cognitive impairment in AD patients, and most AD drugs currently used in clinical or still under development increase BDNF biosynthesis." (PMID 40649806, 2025). "BDNF signaling is deregulated in AD, resulting in cognitive impairment and loss of memory." (PMID 40380033, 2025). "Similarly, in patients with AD, a decrease in blood BDNF level is more closely linked to cognitive impairment compared to vascular dementia." (PMID 40380033, 2025). "Furthermore, increased IL-1β was implicated in the development of cognitive deficits, especially in working memory, probably as a result of altered function of microglia and reduced BDNF production." (PMID 41010622, 2025). "In fact, neurodegenerative disorders such as multiple sclerosis, Alzheimer’s disease, mild cognitive impairment, and Parkinson’s disease, which are linked to lower levels of brain-derived neurotrophic factor, have been studied in terms of the role of physical exercise versus no exercise." (PMID 38610829, 2024). "We hypothesized that BDNF levels may mediate the underlying mechanism of cognitive impairment in lower skeletal muscle mass." (PMID 38559694, 2024). "BDNF gene polymorphisms are a focal point in research on Alzheimer’s disease (AD) and Mild Cognitive Impairment (MCI), revealing their significant role as prognostic markers in memory decline and hippocampal atrophy in MCI patients, and their close association with the progression of MCI." (PMID 39876995, 2024). "Furthermore, the severity of cognitive impairment in patients with PD is linked to the peripheral BDNF level." (PMID 38376038, 2024). "Furthermore, it was demonstrated that Aβ induced hippocampal synapse loss and impaired synaptic plasticity, and cognitive deficits were mediated by alterations in BDNF/CREB signaling." (PMID 39199197, 2024). "Our findings suggest that cognitive impairments in mice repeatedly exposed to ketamine during the neonatal period are associated with downregulated BDNF protein level, synaptic plasticity damage, and decreased excitability of glutamatergic neurons in the hippocampal CA1 region." (PMID 38332635, 2024). "While we did not quantify the BDNF levels in our cohort, our results suggest a potential mechanism for increased levels of BDNF in individuals with the Met allele: BDNF rs6265 Met/Met homozygotes, resulting in depressive symptom‐induced cognitive impairment in female BCS." (PMID 38379321, 2024). "Research has suggested that reduced BDNF levels may be linked to the neurobiology of burnout syndrome and are linked to cognitive deficits." (PMID 38787900, 2024). "Additionally, alterations in plasmatic levels of BDNF are associated with mild cognitive impairment, an intermediate state between normal aging and early dementia." (PMID 37108547, 2023). "Thus, future research should combine more molecular biology and cell biology techniques to further elucidate the role of the MALAT1/miR-382-3p/BDNF signaling pathway in diabetes-associated cognitive impairment." (PMID 37740187, 2023). "Female offspring displayed increased cognitive deficits and anxiety-like behavior following prenatal stress, which were associated with GM alterations in the pregnant females and increased IL-1β and decreased BDNF levels in utero." (PMID 37404311, 2023). "For instance, brain-derived neurotrophic factor (BDNF) was down-regulated in both sexes, consistent with previous findings that a reduction in BDNF is associated with cognitive impairment in AD, whereas elevated BDNF levels can improve cognitive function in an AD mouse model." (PMID 37358952, 2023). "In addition, a considerable amount of evidence suggests that a reduction in the level of BDNF in the PFC (presumably including the hippocampus) is strongly linked to cognitive impairment induced by simulated microgravity." (PMID 37168997, 2023).
Cognitive impairment (continued). "Having shown that the BDNF-TrkB pathway in DG is causally involved in ELS-induced cognitive deficits, we then evaluated the potential therapeutic effects when targeting at the pathway, by systemic administration of TrkB receptor antagonist (ANA-12) and agonist (7,8-DHF)." (PMID 37225683, 2023). "Knowing that patient with DM are susceptible to cognitive impairment and neuropsychiatric disorders, one could suggest that BDNF levels might play a role in DM-mediated cognitive decline." (PMID 36787304, 2023). "Our study found that low BDNF and thrombotic subtype of ischemic stroke may be risk factors for cognitive impairment in the acute poststroke period." (PMID 36969561, 2023). "BDNF, which has links to both neuron regeneration and glucose metabolism, may play a crucial role in the cognitive impairment associated with diabetes." (PMID 36936159, 2023). "An association between cognitive impairment in the poststroke period and lower peripheral levels of BDNF has also been found, which may be related to impaired signalling." (PMID 36969561, 2023). "Moreover, earlier research has linked microglial activation, IL-1β elevation, and BDNF reduction to anesthesia- and surgery-induced hippocampus cognitive impairment." (PMID 36943623, 2023). "However, the prognostic significance of serum BDNF level and clinical characteristics regarding the risk of developing cognitive impairment in the acute period of ischemic stroke remains uncertain." (PMID 36969561, 2023). "An association between cognitive impairment in the poststroke period and lower peripheral BDNF levels is known, but the prognostic significance of serum BDNF levels and clinical characteristics for the risk of developing cognitive impairment in the acute period remains uncertain." (PMID 36969561, 2023). "To examine whether BDNF in DG is causally involved in ELS-induced cognitive deficits, we first evaluated the impact of downregulating BDNF expression in dorsal DG on spatial memory in adult mice." (PMID 37225683, 2023). "We hypothesized that BDNF levels may mediate to explore or understand the underlying mechanism in the cognitive impairment in diabetes." (PMID 36936159, 2023). "Numerous studies have linked BDNF downregulation to the pathogenesis of cognitive disorders, such as Alzheimer’s disease (AD), with low serum levels correlated with AD and mild cognitive impairment, and high serum levels associated with better cognition in healthy older adults." (PMID 37770565, 2023). "Germ-free mice present with social cognitive deficits, which may be associated with biochemical changes, such as decreased hippocampal BDNF and c-FOS expression, important in memory." (PMID 37404311, 2023). "It is hypothesized that each pathway plays an essential role, as strategies that dampen any of these mechanisms individually have been shown to result in defective BDNF expression associated with cognitive impairment." (PMID 37868812, 2023). "Accordingly, it has been shown that interference with the BDNF/TrkB signaling pathway either by genetic manipulations or pharmacological interventions causes memory and cognitive impairments and that chronic BDNF deficiency in BDNF knock out mice results in age-dependent learning deficits." (PMID 38136170, 2023). "In patients with T2DM, lower levels of BDNF have been linked to cognitive impairment." (PMID 38139436, 2023). "It is suggested that combining biological indices such as cytokines and BDNF with magnetic resonance imaging analysis technology can provide new insights into understanding the underlying mechanism of T2DM-related cognitive impairment and further explore biomarkers for its early diagnosis." (PMID 37113152, 2023). "Importantly, the gut microbiota metabolite butyrate was able to counteract those alterations, including cognitive impairment, neuronal spine loss, and BDNF reduction in both in vivo and in vitro studies." (PMID 36787221, 2023).
Cognitive impairment (continued). "Combined, these observations suggest that neuroinflammation and synaptic plasticity-associated proteins, such as PSD-95, SYP, and BDNF, may be involved in the cognitive impairment of offspring induced by maternal inflammation during pregnancy." (PMID 38074521, 2023). "Additionally, DPP-4i restricted diabetes-associated cognitive deficits by modulating neuroinflammatory indicators of caveolin 1 (Cav 1) and brain-derived neurotrophic factor (BDNF), thus reducing inflammatory response in the brain." (PMID 38082288, 2023). "Latest study confirmed the presence of cognitive impairment in the mice with hippocampus of Lipin1-deficient, including the worsen spatial learning and memory ability, decreased synapse number, reduced protein levels of BDNF, SYP and PSD95." (PMID 36918862, 2023). "The Met/Met genotype in the rs6265 polymorphism of the BDNF gene may accelerate cognitive impairment in patients with SIVD, and this effect was correlated with neurodegeneration measured with plasma NfL but independent of vascular lesions." (PMID 37876876, 2023). "Moreover, TBI-associated physiological and cognitive deficits are attenuated by upregulation in levels of brain-derived neurotrophic factor (BDNF) and inhibition of glycogen synthase kinase-3 (GSK-3) activity via activation of upstream Akt." (PMID 36016833, 2022). "The interaction between the synaptic vesicle-associated proteins and BDNF might trigger the imbalance of synaptic plasticity that occurs in cognitive impairment." (PMID 35910680, 2022). "In the present study, we found that the level of BDNF in rats with cognitive impairment was significantly lower than that in the normal control group, suggesting that the decrease in BDNF content also underlies the cognitive impairment in premature rats." (PMID 36061856, 2022). "In summary, the potential mechanism of sevoflurane-induced cognitive impairment is associated with the inhibition of AHN in SGZ which may involve the BDNF/TrkB and NT-3/TrkC pathways." (PMID 35309893, 2022). "It will be important to identify whether the decrease in BDNF observed in BD could be associated with present or ulterior cognitive impairment in BD." (PMID 35740389, 2022). "Moreover, the molecular mechanism of zinc deficiency-induced cognitive impairment is associated with hippocampal BDNF DNA methylation." (PMID 35090576, 2022). "Low BDNF is associated with cognitive impairment in patients with Parkinson’s disease." (PMID 35743271, 2022). "Memory and cognitive defects have been associated with deregulation of BDNF, m RNA and protein." (PMID 35692417, 2022). "However, the association of BDNF levels in the brain or peripheral blood with cognitive impairment in AD is quite complex and influenced by many factors, such as sample heterogeneity and methodological differences." (PMID 36425322, 2022). "Several recent meta-analyses analyzed the association between BDNF and AD cognitive impairment and found that the results are inconsistent or even contradictory, and higher, lower, or similar levels of circulating BDNF have all been reported in AD or MCI patients compared to healthy controls." (PMID 36425322, 2022). "In T2DM mouse models, researchers have found that downregulation of GPR40 correlates with decreased expression of brain-derived neurotrophic factor (BDNF), which might be an underlying molecular mechanism associated with cognitive impairment in diabesity." (PMID 35335269, 2022). "Additionally, BDNF Val66Met polymorphism has shown protective roles against cognitive impairment in PwMS." (PMID 35239684, 2022). "Reduced hippocampal BDNF is associated with cognitive deficits in diabetic patients." (PMID 35884825, 2022). "BDNF expression is reduced following prenatal alcohol exposure, and this reduction in BDNF levels could result in alterations in other signaling pathways that ultimately cause cognitive impairment." (PMID 36552126, 2022).
Cognitive impairment (continued). "Factors influencing the association between plasma BDNF and cognitive impairment." (PMID 36425322, 2022). "P75NTR inhibitor and exogenous BDNF could attenuate cognitive deficits by rescuing the dendritic spine loss and long-term potentiation (LTP) via altering the BDNF/proBDNF ratio." (PMID 35370607, 2022). "In these patients, negative symptoms partially mediated the relationship between age of onset and cognitive deficits, which was moderated by serum BDNF and Val66Met polymorphism, since the mediating effect of negative symptoms exhibited a Met allele dose-dependent tendency." (PMID 34220575, 2021). "Despite appreciating many established associations between variations of BDNF gene in stroke with cognitive impairment and psychiatric disorders, the pondering question is whether BDNF can be considered a “disease susceptibility gene”." (PMID 34367374, 2021). "In conclusion, educational history and a simple cognitive evaluation, together with the measurement of BDNF, allowed us to identify patients who are at risk of cognitive impairment and differentiate them from those who are already cognitively impaired, stratifying them in a very clear way." (PMID 34341419, 2021). "BDNF rs56164415 was reported to be associated with cognition in neurodegenerative disorders since the T allele was more frequently found in patients with Alzheimer’s disease (AD), characterized with significant cognitive impairment." (PMID 33926045, 2021). "Furthermore, BDNF can reverse neuron loss, improve cognitive impairment, and provide substantial protection for important neural circuits associated with AD." (PMID 33732137, 2021). "Aging is also characterized by decreased concentration of BDNF, suggesting that the salvage of the BDNF could significantly underlies the retrieve of cognitive impairment." (PMID 33642976, 2021). "A meta-analysis showed that patients with cognitive impairment may be associated with a reduction in peripheral BDNF." (PMID 34941076, 2021). "Further biological and longitudinal studies with larger samples are needed to elucidate the underlying mechanism underlying the association between low BDNF serum levels and cognitive deficits in LLS patients, and how aging and schizophrenia interact in cognitive changes." (PMID 34239458, 2021). "Reduced brain-derived neurotrophic factor (BDNF), a protein critical for neural plasticity and synaptic signaling, is one of the few molecules consistently associated with cognitive deficits in schizophrenia although the etiological pathway leading to BDNF reduction in schizophrenia is unclear." (PMID 33558459, 2021). "SGLT2i may thus bring benefits to diabetic patients with atherosclerosis by preventing cognitive impairment associated with low levels of BDNF." (PMID 34885795, 2021). "Low BDNF levels were associated with cognitive impairment in a human study." (PMID 34640355, 2021). "Choline supplementation during specific pre- and postnatal time windows reverses some cognitive deficits observed in a rodent model of fetal-neonatal ID associated with increased expression of neurotrophic factors such as brain-derived neurotrophic factor (BDNF)." (PMID 34960080, 2021). "In general, CREB/BDNF pathway may underlie the acer truncatum seed oil elevated expression of synaptic proteins in the aging mice to alleviate cognitive impairment." (PMID 34055809, 2021). "In addition, modulation of gut microbiota using antibiotics reduces induced cognitive deficits associated with decreasing BDNF levels in the adult brain." (PMID 33691793, 2021). "In addition, genetic studies on human AD patients have reported that BDNFVal66Met SNP, known to reduce synaptic BDNF release, is associated with greater cognitive impairment and higher vulnerability of hippocampus-frontal connectivity to primary AD pathology." (PMID 34071457, 2021).
Cognitive impairment (continued). "In summary, our study demonstrated that neuroinflammation overactivated NMDARs, at least in part, plays a key role in overactivation of calpain, cleavage of TrkB-FL receptor, BDNF/TrkB signaling dysfunction, dendritic spine loss, cell apoptosis, and consequent cognitive impairments." (PMID 31948437, 2020). "Our findings revealed that BDNF Met/Met genotype and lower plasma levels may be susceptible to cognitive impairments in PD patients." (PMID 33047489, 2020). "Under this hypothesis, our study showed that prenatal long-term mobile phone exposure can cause cognitive impairment, changes in hippocampal morphology and synaptic ultrastructure, decreased expression of synaptic proteins, and BDNF in the elderly offspring." (PMID 32581772, 2020). "In addition, HFD reduced BDNF, which is associated with hippocampal synaptic plasticity, leading to cognitive impairment." (PMID 33312340, 2020). "The BDNF Met/Met genotype may be associated with lower BDNF plasma levels and cognitive impairments in PD patients." (PMID 33047489, 2020). "A decrease in serum BDNF levels is associated with cognitive impairment in dementias and changes in BDNF levels in the hippocampus may be linked with emotional symptoms relating to Alzheimer’s disease." (PMID 33505247, 2020). "However, few studies have focused on the relationships between BDNF gene polymorphisms, BDNF plasma levels, and cognitive impairment in patients with PD." (PMID 33047489, 2020). "This cognitive deficit might be associated with changes in the expression of cognition-relevant signaling molecules such as brain-derived neurotrophic factor (BDNF), N-methyl-D-aspartate receptor subunit 2B, serotonin transporter and neuropeptide Y system." (PMID 32082260, 2020). "The p.Val66Met SNP substitutes a valine (Val) residue at position 66 with a methionine (Met) residue in the pro-domain of the BDNF protein.The Met allele has been found to be associated with cognitive impairments in PD patients and late-life psychiatric symptoms in the general population." (PMID 33584494, 2020). "Anesthesia and surgery-induced neuroinflammation overactivated NMDARs and then triggered overactivation of calpain, which subsequently led to the truncation of TrkB-FL, BDNF/TrkB signaling dysregulation, dendritic spine loss, and cell apoptosis, contributing to cognitive impairments in aging mice." (PMID 31948437, 2020). "In the neuronal pathway, the hippocampal BDNF concentration is decreased by antibiotic-induced gut dysbiosis, which could cause cognitive impairment." (PMID 32825437, 2020). "Some studies reported that interactions between inflammatory factors and BDNF may be implicated in the pathophysiology and cognitive impairment seen in chronic schizophrenia." (PMID 31420036, 2019). "Deficits in these synaptoplastic processes may underlie some of the cognitive deficits exhibited by patients with schizophrenia, which is closely related to imbalanced circuit-level expression of BDNF signaling molecules." (PMID 31396062, 2019). "Interestingly, our own recent study showed that decreased BDNF levels were associated with cognitive impairment, especially immediate memory in schizophrenia." (PMID 30659208, 2019). "In clinics, BDNF depletion in brain (up to 70% in SN and 80% in DOPAn) has been correlated with DOPAn loss, and BDNF decrease in the serum of PD patients has been reported correlating with the timing from diagnosis, pathology severity, and cognitive deficit." (PMID 31064126, 2019). "Since BDNF contributes to the plasticity and repair of DA neurons and a lower BDNF level is associated with greater cognitive impairments in PD patients, this suggests that miR-30a may play a neurotoxic role in PD." (PMID 31718095, 2019).